APOC1 (apolipoprotein C1)
Diseases named in the same sentence as APOC1 in open-access papers (continued):
Sharing a sentence is not in itself a finding about the gene and the disease.
atherosclerosis (continued). "Although this effect might be protective against infection and sepsis, the presence of apoC1 was shown to enhance atherosclerotic lesion size and inflammatory status of the plaque in a genetically engineered mice where atherosclerosis was induced by repeated LPS injections." (PMID 36471375, 2022). "In this review we will present data on apoC1 structure and distribution among lipoproteins, on the effects of apoC1 on VLDL metabolism and HDL metabolism and we will discuss the possible links between apoC1, atherosclerosis and diabetes." (PMID 36471375, 2022). "This reduction, in systemic ApoC1 production, is a component of the postulated mechanism for S. mansoni-related protection from HFD- induced atherosclerosis." (PMID 30483256, 2018). "Whether these structural modifications contribute to, or are a consequence of atherosclerosis is not known but, in a similar manner to what was observed with glycation phenomena in diabetic subjects, they might be associated with alterations of apoC1 functionality." (PMID 36471375, 2022). "Human apoC1 prevented extension of aortic atherosclerotic lesions in rabbits fed with cholesterol-rich diet while, on the opposite, CETP activity was found to be correlated positively with the extent of atherosclerosis." (PMID 36471375, 2022). "Strikingly, it appears that the balance between protective and deleterious effects of apoC1 mostly rely on the presence of CETP in the experimental models, as illustrated, among others by opposite effects human apoC1 on atherosclerosis between mice and rabbits." (PMID 36471375, 2022). "However, studying the lipid mediated effects of apoC1 on atherosclerosis in mice is hampered by the absence of CETP in this species, which leads to overlooking the possible impact of apoC1 on CETP-mediated remodelling of HDL as occurs in humans." (PMID 36471375, 2022).
hyperlipidemia (21 papers, 2011 to 2024). "Elevated ApoC1 levels were associated with carotid intima media thickness, hyperlipidemia, and aggravated coronary artery disease in both animals and humans." (PMID 35885984, 2022). "Overexpression of human apolipoprotein C1 (APOC1) with hyperlipidemia in transgenic mice causes hair growth issues corresponding to the grade of expression of human APOC1 genes in the skin." (PMID 31100937, 2019). "Over-expression of human apolipoprotein C1 (APOC1) with hyperlipidemia in transgenic mice causes hair growth disorders correlated with the level of expression of human APOC1 gene in the skin." (PMID 30154860, 2018). "As a matter of fact, previous studies performed in humans and mice have connected the effects of increased APOC1 in combined hyperlipidaemia with a more pronounced impact on circulating triglycerides." (PMID 39362599, 2024). "APOC1 has been reported to have an additional role in epidermal lipid synthesis as well as adipose tissue formation due to hyperlipidemia in transgenic mice overexpressing Apoc1." (PMID 37197688, 2023). "In vivo, the overexpression of human APOC1 in mice led to hyperlipidemia owing to the reduced uptake of VLDL and post-lipolysis particles by inhibiting the binding of VLDL to VLDLR." (PMID 32974161, 2020). "In vivo, human apoC1 overexpression in mice led to hyperlipidemia due to the reduced uptake of VLDL and post-lipolysis particles by inhibiting binding to VLDLR." (PMID 31779116, 2019). "Overexpression of human apolipoprotein C1 (APOC1) with hyperlipidemia in transgenic mice results in abnormal hair growth correlated with the expression of the human APOC1 gene in the skin." (PMID 28904532, 2017). "The overexpression of human APOC1 has been demonstrated to produce hyperlipidemia and increase serum lipid levels." (PMID 27416065, 2016). "Further potential confounding factors influencing ApoC1 serum levels include the BMI of individual patients, underlying hyperlipidemia or vascular diseases, and last but not least, metabolic changes induced by general anesthesia or intraoperative blood loss." (PMID 36101402, 2022). "Additionally, a previous report has indicated that ApoC1 production drives hyperlipidemia and pathogenesis in the ApoE−/− model, making it a likely candidate for correlation with reduced plaque formation during infection." (PMID 30483256, 2018). "In addition, apoC1 loses its ability to inhibit CETP in a context of hyperlipidemia and diabetes." (PMID 36471375, 2022). "Among these are rs2284017 (CACNG2) for lithium (as treatment for Bipolar Disorder), rs1801252 (ADRB1) for atenolol (Coronary Artery Disease), and rs429358 (APOC1, APOE) for ritonavir (HIV, HIV infections, Hyperlipidemias)." (PMID 23758991, 2013). "A loss of the negative correlation between apoC1 and CETP activity was observed in patients with type 1 or type 2 diabetes, similarly to what was reported CAD patients with hyperlipidemia." (PMID 36471375, 2022). "Moreover, in APOE knock-out mice, endogenous apoC1 inhibited LPL, depending on its expression level, subsequently increasing VLDL and inducing hyperlipidemia." (PMID 31779116, 2019). "The present study demonstrated a significant upregulation in several apolipoproteins, including APOC1, APOB, APOC4 and APOL1, but also in LCAT, suggesting a dysregulation in lipoprotein metabolism that could be partially related to the hyperlipidemia in IMN patients." (PMID 37511514, 2023). "Indeed, 49% of apoC1 is associated with VLDL in subjects with hypertriglyceridemia and 43% in subjects with combined hyperlipidemia (high level of triglycerides and LDL cholesterol), whereas the relative amounts of apoC1 in HDL decreased (respectively 51% and 57%)." (PMID 36471375, 2022).
hyperlipidemia (continued). "However, this negative correlation between apoC1 levels and CETP activity was lost in CAD patients with hypertriglyceridemia or combined hyperlipidemia." (PMID 36471375, 2022).
diabetes (20 papers, 2010 to 2025). "To date, few studies have examined the potential association between apoC1 gene polymorphisms and diabetes." (PMID 41356011, 2025). "A small cohort study involving individuals of American Indian or Mexican descent identified the T45S structural variant of apoC1, which predisposes the protein to N-terminal truncation and was associated with an increased risk of obesity-related diabetes." (PMID 41356011, 2025). "Abnormal ApoC1 levels are associated with cardiovascular diseases, diabetes, and cognitive dysfunction." (PMID 37685872, 2023). "In the context of diabetes, apoC1 would thus appear as positively associated with some cardiometabolic risk factors." (PMID 36471375, 2022). "However, associations of APOC1 expression are negatively correlated with GFR in Woroniecka Diabetes Tublnt cohorts (R2 = 0.552, P = 0.014)." (PMID 36891052, 2023). "However, the causal relationship between high apoC1 levels and diabetes is questionable." (PMID 36471375, 2022). "By controlling the plasma levels of lipids, apoC1 relates directly to cardiovascular physiology, and also links to other functions including inflammation and immunity, sepsis, diabetes, cancer, and viral infectivity." (PMID 41356011, 2025). "Beyond the use of apoC1 level as a new marker of diabetes severity, the restoration of apoC1 functionality might help to counteract the deleterious effects of increased CETP activity on plasma lipoprotein profile in this population at high cardiovascular risk." (PMID 36471375, 2022). "Interestingly, plasma apoC1 concentration was positively correlated with the level of triglycerides, but not that of visceral fat in both type 1 and type 2 diabetes." (PMID 31779116, 2019). "Overall, these results demonstrate that apoC1 plays a role in the evolution of diabetes, and further studies in this direction may lead to a better understanding of the connection between lipid and glucose metabolism." (PMID 31779116, 2019). "Furthermore, ApoA1 plasma concentration was decreased, whereas ApoC1 and ApoH were increased in the patients with CAD and/or diabetes." (PMID 37686357, 2023). "The functionality of apoC1 on CETP activity is impaired in diabetes that might account, at least in part, for the increased plasma CETP activity observed in patients with diabetes." (PMID 36471375, 2022). "By controlling the plasma levels of lipids, apoC1 relates directly to cardiovascular physiology, but its activity extends beyond, to inflammation and immunity, sepsis, diabetes, cancer, viral infectivity, and—not last—to cognition." (PMID 31779116, 2019).
Obesity (19 papers, 2015 to 2025). Accumulation of substantial excess body fat. "The association of the rs4420638 polymorphism, near the APOC1 gene, was examined with the risk of obesity among Portuguese children." (PMID 37328602, 2024). "In conclusion, the present study provides further evidence for the APOE/APOC1 candidate-region association with the risk of obesity, in particular in children." (PMID 37328602, 2024). "Apolipoprotein C1 overexpression in transgenic mice has been associated with protection from obesity and insulin resistance." (PMID 27795741, 2016). "In this study, we examined the association of the polymorphism rs4420638 A > G, tagging the LD block harboring the APOE and APOC1 genes, with the risk of obesity using BMI case-control groups of Portuguese children (normal-weight vs. overweight, including obesity)." (PMID 37328602, 2024). "It was reported that T45S exhibited a stronger preference towards VLDL than to HDL and also in one study, based on 410 Canadian Oji-Cree individuals, where the frequency of the S45 allele was 8%, it was associated with reduced obesity and decreased plasma concentrations of leptin and apoC1." (PMID 31779116, 2019). "Germ-free mice receiving a high fat diet together with Enterobacter cloacae B29 from a morbidly obese volunteer donator exhibited increased inflammation and obesity and altered lipid metabolism with decreased apoC1." (PMID 31779116, 2019). "Empagliflozin may protect the heart by altering the expression of genes including Apoe, Apoc1, Saa2, Apoa2, and Pon1, which are all involved in lipid metabolism disturbance in obesity." (PMID 36242090, 2022). "There are, however, less investigations on Apoc1 and obesity-related heart damage." (PMID 36242090, 2022). "GCKR, ABCB11, CDKAL1, CDKN2B, NT5C2, and APOC1 were associated with metabolically unhealthy phenotypes in individuals with normal weight but not in those with obesity." (PMID 33500527, 2021). "GCKR, ABCB11, CDKAL1, CDKN2B, NT5C2, and APOC1 were associated with metabolically unhealthy in individuals with normal weight but not in those with obesity." (PMID 33500527, 2021). "One study reported that ApoC1 transgenic mice were protected from obesity and insulin resistance." (PMID 34586189, 2021). "The down-regulation of Apoc1 in the HFD+B29 mice might be responsible for the occurred obesity, insulin resistance and higher plasma cholesterol level." (PMID 27877172, 2016). "The overexpression of human apolipoprotein C1 (Apoc1) in mice could protect mice from obesity and insulin resistance whereas Apoc1 deficient mice usually had decreased HDL-cholesterol levels." (PMID 27877172, 2016). "This variant, near the APOC1 gene, have been reported to exist in LD with APOE ε2/ε3/ε4 polymorphisms, and it is unknown whether these associations are independent of the APOE alleles that are known to increase the risk of obesity." (PMID 37328602, 2024). "Further examination of DEPs revealed that following empagliflozin treatment, the expressions of Apoe, Apoc1, Saa2, Apoa2, and Pon1 altered dramatically, suggesting that these proteins may be the main proteins that empagliflozin uses to treat obesity-induced aberrant lipid metabolism." (PMID 36242090, 2022). "He found GCKR, ABCB11, CDKAL1, CDKN2B, NT5C2, and APOC1 gene were associated with metabolically unhealthy phenotypes in individuals with normal weight but not in those with obesity, showing that certain genetic polymorphisms may also have an impact on the metabolic health in NWO populations." (PMID 39777912, 2025). "Among the proteins upregulated in obesity, CRP, C9, and APOC1 not only showed elevated abundance but also demonstrated strong, consistent links across metabolic, vascular, and inflammatory domains." (PMID 40981199, 2025).
colorectal cancer (18 papers, 2011 to 2024). A primary or metastatic malignant neoplasm that affects the colon or rectum. "Several researches revealing APOC1 to be a diagnostic and prognostic marker for gastric cancer and colorectal cancer." (PMID 35646092, 2022). "Similar findings were made in pancreatic and colorectal cancer, where APOC1 overexpression is associated with poor prognosis." (PMID 32665538, 2020). "According to additional research, APOC1 overexpression aids in the progression of liver metastases in colorectal cancer." (PMID 38067270, 2023). "In colorectal cancer, APOC1 modulates cell proliferation and motility via the mitogen-activated protein kinase (MAPK) pathway." (PMID 37576389, 2023). "Loss of FUS function leads to impaired cellular proliferation and marked increases in phosphorylated histone H3, whereas APOC1 promotes tumor progression via MAPK signaling as shown for colorectal cancer and maintains cell survival by preventing apoptosis." (PMID 37208732, 2023). "Correlation analysis revealed that APOC1 was negatively regulated by hsa-miR-335-5p in colorectal cancer (r = -0.27, P < 0.001)." (PMID 34081622, 2021). "APOC1 is also reported to promote colorectal cancer proliferation, migration and invasion by activating the MAPK pathway." (PMID 34298684, 2021). "Nevertheless, the correlation analysis revealed that APOC1 gene was negatively regulated by miR-335-5p in colorectal cancer." (PMID 34081622, 2021). "In colorectal cancer, APOC1 played its proliferative activity by MAPK signaling, and in pancreatic cells it was found to inhibit apoptosis." (PMID 32974161, 2020). "There were some evidences that APOC1 facilitated tumor progression in colorectal cancer through the MAPK signaling pathway." (PMID 31573738, 2019). "Similarly, the overexpression of ApoC1 mRNA has been analyzed in a multitude of malignancies, especially renal cancer and colorectal cancer, but also gynecological tumors, prostate cancer and pancreatic or gastric carcinoma." (PMID 36216850, 2022). "Only three upregulated genes (APOC1, CYP2E1, HPR) were significant in term of prognosis, suggesting that these three genes could be associated with prognosis in colorectal cancer patients." (PMID 34081622, 2021). "According to our results, we propose for the first time that APOC1 could play a crucial role in liver metastasis of colorectal cancer." (PMID 34081622, 2021). "For example, apolipoprotein C1 (APOC1), which was ranked as the top protein, is significantly decreased in samples of cancer patients and has been previously reported to be down-regulated in the non-small lung cancer, colorectal cancer, papillary thyroid carcinoma, and pediatric nephroblastoma." (PMID 38529947, 2024). "A progressive increase was observed in the expression of APOC1 from normal tissue to primary tumor tissues and liver metastatic tumor tissues in colorectal cancer, suggesting that APOC1 could have a significant role in the pathology of liver metastasis in colorectal cancer." (PMID 38067270, 2023). "In colorectal cancer (CRC), ZEB1-AS1 promotes liver metastasis via the miR-335-5p/APOC1 axis." (PMID 37305389, 2023).
pancreatic cancer (17 papers, 2010 to 2023). "Elevation of APOC1 expression was associated with tumor cell survival in pancreatic cancer." (PMID 22606345, 2012). "Elevated serum APOC1 was observed in patients with pancreatic cancer, gastric cancer, and triple-negative breast cancer." (PMID 35765478, 2022). "Several studies declared that ApoC-1 mediates cell survival and the knockdown of ApoC-1 significantly has decreased proliferation of pancreatic cancer cells and induced apoptosis." (PMID 36381193, 2022). "The correlation of high tissue expression and high preoperative serum concentration of ApoC-1 with poor prognosis of pancreatic cancer patients has been reported by Li and colleagues." (PMID 36381193, 2022). "On the other hand, Li and colleagues reported reduction of serum ApoC-1 level of pancreatic cancer patients after surgery compared to the preoperative serum confirming that pancreatic cancer cells secrete ApoC-1." (PMID 36381193, 2022). "APOC1 has been observed to be overexpressed in colorectal, lung, pancreatic cancer and renal cell carcinoma." (PMID 34298684, 2021). "APOC1 was overexpressed in pancreatic cancers and an increased level of APOC1 in preoperative serum of patients was considered to reflect an unfavorable prognosis." (PMID 31573738, 2019). "High preoperative serum levels of APOC1 have been shown to correlate with poor prognosis in pancreatic cancer patients." (PMID 29630649, 2018). "In pancreatic cancer, serum APOC1 derived from cancer cell serves as a prognostic symbol." (PMID 33430855, 2021). "Apolipoprotein C-1 (APOC1) protein is highly expressed in pancreatic cancer." (PMID 27228351, 2016).